TRPS1 (transcriptional repressor GATA binding 1)
Description:
Transcriptional repressor. Binds specifically to GATA sequences and represses expression of GATA-regulated genes at selected sites and stages in vertebrate development. Regulates chondrocyte proliferation and differentiation. Executes multiple functions in proliferating chondrocytes, expanding the region of distal chondrocytes, activating proliferation in columnar cells and supporting the differentiation of columnar into hypertrophic chondrocytes.
Synonyms: LGCR; GC79
Tractability: PROTAC: UniProt records ubiquitination sites on it; ubiquitination databases record sites on it.
Gene: Protein-coding gene on chromosome 8 (115,408,496 to 115,809,673, reverse strand). Ensembl gene ENSG00000104447.
Subcellular location: Nucleus
Subcellular location (Human Protein Atlas): Nucleoplasm
Gene Ontology:
Molecular function: DNA-binding transcription repressor activity, RNA polymerase II-specific; protein binding; protein domain specific binding; RNA polymerase II transcription regulatory region sequence-specific DNA binding; DNA-binding transcription factor activity; zinc ion binding; sequence-specific DNA binding
Biological process: negative regulation of transcription by RNA polymerase II; skeletal system development; regulation of chondrocyte differentiation; regulation of transcription by RNA polymerase II; negative regulation of DNA-templated transcription; regulation of DNA-templated transcription
Cellular component: chromatin; nucleoplasm; nucleus; protein-containing complex
Genetic constraint (gnomAD): Loss-of-function variants: 6 observed, 104.22 expected, observed/expected ratio (o/e) 0.0576, 90% interval 0.031 to 0.11. The upper end of that interval is the gene's LOEUF score, 0.11, which puts it in group 1 of 6, group 1 being the genes least tolerant of losing a copy. Missense variants: 1,359 observed, 1,647.7 expected, observed/expected ratio (o/e) 0.82, 90% interval 0.79 to 0.86. Synonymous variants: 578 observed, 620.23 expected, observed/expected ratio (o/e) 0.93, 90% interval 0.87 to 1.
Homologues: Orthologues: chimpanzee TRPS1 (99% identical), macaque TRPS1 (99% identical), rabbit TRPS1 (95% identical), pig TRPS1 (95% identical), guinea pig TRPS1 (93% identical), mouse Trps1 (92% identical), rat Trps1 (92% identical), tropical clawed frog trps1 (75% identical), zebrafish trps1 (51% identical), Drosophila melanogaster srp (9% identical), Drosophila melanogaster GATAd (9% identical), Caenorhabditis elegans elt-2 (4% identical), and 1 more. Paralogues in human: GATA2 (9% identical), GATA3 (8% identical), GATA6 (7% identical), GATA1 (7% identical), GATA5 (7% identical), GATA4 (7% identical), ZGLP1 (4% identical).
Diseases named in the same sentence as TRPS1 in open-access papers:
TRPS1 is named in the same sentence as 167 diseases in open-access papers, as found by Europe PMC text mining. Sharing a sentence is not in itself a finding about the gene and the disease. The quoted sentences say what the papers report.
breast carcinoma (84 papers, 2004 to 2025). "Trichorhinophalangeal syndrome type 1 (TRPS1) is a GATA family of zinc transcription factors implicated in breast cancer carcinogenesis and involved in cancer cell survival." (PMID 40025593, 2025). "Common genetic variants in the repressive GATA-family transcription factor (TF) TRPS1 locus are associated with breast cancer risk, and luminal breast cancer cell lines are particularly sensitive to TRPS1 knockout." (PMID 38377146, 2024). "In contrast, higher TRPS1 expression has been associated with better breast cancer patient outcomes, though its expression is highly correlated with ER and GATA3, both favorable prognostic indicators." (PMID 38377146, 2024). "This TRPS1-regulated transcription appears to be relevant for cancer cell fitness, as TRPS1 depletion decreases cell number doubling rate, and high TRPS1 activity is associated with worse breast cancer patient outcomes." (PMID 38377146, 2024). "We focused on TRPS1 based on two orthogonal, genome-wide, unbiased assays that implicated TRPS1 in the processes of breast tumor incidence and breast cancer cell number accumulation." (PMID 38377146, 2024). "First, we used the summary statistics from a recent GWAS to plot two sets of common genetic variants in the TRPS1 locus associated with breast cancer incidence." (PMID 38377146, 2024). "Here, we show that elevated expression of transcriptional repressor GATA binding 1 (TRPS1) is associated with lower drug sensitivity, reduced response rate, and poor prognosis in chemotherapy-treated breast cancer patients." (PMID 39276941, 2024). "The utility of TRPS1 extends beyond breast cancer, with studies demonstrating its diagnostic potential in a range of other tumor types, including prostate, lung, and gastrointestinal cancers." (PMID 39518009, 2024). "TRPS1 has emerged as a valuable immunohistochemical marker in the diagnostic evaluation of breast cancer, particularly in distinguishing primary breast tumors from metastatic lesions." (PMID 39518009, 2024). "In breast cancer, the loss of TRPS1 along with loss/inactivation of E-cadherin results in increased proliferation of mammary organoids and accelerated tumorigenesis in mouse models." (PMID 37176013, 2023). "Common genetic variants in the TRPS1 locus are associated with breast cancer risk, and luminal breast cancer cell lines are particularly sensitive to TRPS1 knockout." (PMID 37461612, 2023). "Essential genes associated with essential binding sites include estrogen receptor 1 (ESR1), the master transcription factor for ER+ breast cancer cells, and TRPS1, another transcription factor that is known to be associated with ER+ breast cancer progression." (PMID 31727847, 2019). "ER1, GATA3 and Trps1 are among the genes that are highly expressed in the E13.5 mouse mammary gland and have also been implicated in human breast cancer." (PMID 26215676, 2015). "Our findings therefore strongly suggest that the TRPS1/Cath-D interplay is implicated in the progression of luminal ER+ breast cancer." (PMID 26183398, 2015). "Next, we investigated the expression of TRPS1 in primary human breast cancer samples and explored its association with major breast tumour histological specialties and patients’ clinical characteristics." (PMID 24934762, 2014). "Based on our findings, we conclude that TRPS1 is positively associated with E-cadherin and β-catenin status in ERα-positive breast cancer cells, while it is also significantly associated with mesenchymal markers of EMT in ERα-negative breast cancer cells." (PMID 24934762, 2014). "TRPS1 (Tricho-rhino-phalangeal syndrome 1) is a GATA transcriptional activator gene encoding for a protein used as a sensitive immunohistochemical marker of breast carcinomas." (PMID 39449380, 2024). "However, in this case the nearest gene is almost a megabase upstream from TRPS1, suggesting that TRPS1 contributes to the breast cancer susceptibility associated with one or both of these sets of genetic variants." (PMID 38377146, 2024).
breast carcinoma (continued). "Furthermore, centralized validation studies involving multi-institutional cohorts would help to assess the reproducibility of TRPS1 staining in different tumor contexts, ensuring that TRPS1 can be reliably used as a diagnostic marker beyond breast carcinoma." (PMID 39518009, 2024). "Finally, we show that high TRPS1 activity, calculated using a gene expression signature defined by primary TRPS1-regulated genes, is associated with worse breast cancer patient prognosis." (PMID 37461612, 2023). "Recent findings have suggested that immunohistochemical stain for trichorhinophalangeal syndrome type 1 (TRPS1) is a more sensitive and specific marker than GATA3 for breast carcinoma, and TRPS1 is especially useful as a diagnostic tool for triple‐negative breast cancers." (PMID 36281523, 2023). "TRPS1 is a known GATA transcriptional repressor that is implicated in breast cancer." (PMID 33548228, 2021). "High TRPS1 activity was also associated with decreased survival in lymph node-positive patients suggesting that TRPS1 independently contributes to the aggressiveness of breast cancer cells." (PMID 30082728, 2018). "To better understand the biological functions of TRPS1 associated with its transcriptional repression function in breast cancer pathogenesis, we performed pathway enrichment analysis on the genes directly targeted and transcriptionally repressed by TRPS1 using DAVID23." (PMID 30563971, 2018). "Consistent with our hypothesis, significant association was also found between TRPS1 expression and E-cadherin expression in ERα + breast cancer cases." (PMID 24934762, 2014). "However, Cath-D and TRPS1 also co-inhibit transcription of genes implicated in tumor progression, as shown for PTHrP that encodes a secreted factor driving bone metastasis formation in breast cancer." (PMID 26183398, 2015). "In recent years, a new marker, trichorhinophalangeal syndrome type 1, also known as transcriptional repressor GATA binding 1 (TRPS1), has been found to be a breast cancer marker with high specificity and sensitivity." (PMID 40822238, 2025). "In summary, our study establishes that a notable proportion of breast AS expresses TRPS1, challenging the previously asserted high specificity of TRPS1 for breast carcinomas." (PMID 38902365, 2025). "They found that TRPS1 was highly expressed at mRNA level across all breast cancer subtypes among 31 different solid tumors studied." (PMID 40025593, 2025). "A promising alternative is TRPS1, which has garnered attention due to its widespread expression, regardless of hormone receptor status, making it a versatile marker in breast carcinoma diagnostics." (PMID 38902365, 2025). "In this retrospective study, we reviewed TRPS1 IHC performed at our center between 07/2022 and 06/2024, to evaluate the expression of TRPS1 in breast carcinoma (primary and distant metastasis) and in other malignancies." (PMID 40025593, 2025). "TRPS1 is a relatively new immunohistochemical (IHC) marker that has demonstrated higher sensitivity in breast cancer, including TNBC." (PMID 40025593, 2025). "The trichorhinophalangeal syndrome protein 1 (TRPS1), once regarded as highly specific for breast carcinomas, now faces doubts regarding its reliability." (PMID 38902365, 2025). "As a marker with high expression in breast cancer, TRPS1 shows diffuse and consistent positivity in 93.2% of breast cancer cases." (PMID 40636692, 2025). "Two studies on TRPS1 in metastatic breast cancer cytological samples indicated that the positivity rates of TRPS1 and GATA3 were similar (7/9 vs. 6/9; 5/7 vs. 5/7)." (PMID 40822238, 2025). "Recent studies reveal that TRPS1 shows a positivity rate exceeding 90% in most special types of breast cancer, including 100% positive expression in adenoid cystic carcinoma and secretory carcinoma." (PMID 40822238, 2025).
breast carcinoma (continued). "This threshold had been previously established by our group in testing TRPS1 expression in breast carcinomas, aligning with the approach used by the group of Wang and colleagues." (PMID 38902365, 2025). "Our group reinforced the value of TRPS1 expression in breast carcinomas with a triple-negative phenotype." (PMID 38902365, 2025). "It is notable that TRPS1 positivity was 100% in all special type breast cancers in this cohort, including metaplastic carcinoma, whereas the positivity rate of metaplastic carcinoma was low with SOX10 and GATA3." (PMID 40025593, 2025). "In contrast, breast carcinoma is marked by elevated TRPS1 expression, underscoring its significance in carcinogenesis and tumor cell survival." (PMID 38902365, 2025). "TRPS1 has emerged as a significant immunohistochemical marker in the diagnosis of breast carcinoma, particularly due to its sensitivity in distinguishing breast cancer from other malignancies." (PMID 39518009, 2024). "This review aims to provide a comprehensive overview of the application of TRPS1 as an IHC marker in breast cancer pathology, focusing on its role in differentiating primary breast cancers from metastatic lesions." (PMID 39518009, 2024). "TRPS1 is an emerging immunohistochemical marker that has been used as a sensitive and specific marker of breast carcinoma and of mammary and extramammary Paget’s disease." (PMID 39449380, 2024). "While TRPS1 is consistently expressed in the majority of breast carcinomas, particularly in luminal and triple-negative subtypes, there are documented cases of TRPS1-negative breast carcinomas." (PMID 39518009, 2024). "It is now well established that TRPS1 can act as a context-dependent oncogene in several breast cancer subtypes." (PMID 38702730, 2024). "TRPS1 negativity in breast carcinomas can lead to difficulties in confirming a breast origin, especially when other breast-specific markers, such as GATA3 or ER, are also absent." (PMID 39518009, 2024). "TRPS1, on the other hand, is thought to have a more restricted expression pattern, making it a more reliable marker in distinguishing breast cancer from other malignancies." (PMID 39518009, 2024). "We inserted an inducible degron tag into the endogenous TRPS1 locus in the luminal breast cancer cell line T47D." (PMID 38377146, 2024). "Altogether, we provide a systematic study of the primary effects of rapid TRPS1 depletion in luminal breast cancer cells." (PMID 38377146, 2024). "In our CUT&RUN experiments from freshly sorted mouse mammary gland cells, we observed a strikingly different binding behavior of TRPS1 compared to ChIP-Seq experiments from cultured breast cancer cells." (PMID 38702730, 2024). "Taken together, our findings provide new mechanistic insights into the DDR and chemoresistance in breast cancer patients and identify TRPS1 as a critical DDR protein." (PMID 39276941, 2024). "TRPS1 expression has been reported in a subset of ovarian and endometrial cancers, although its expression is typically lower than in breast cancer." (PMID 39518009, 2024). "Next we sought to determine how TRPS1 regulates its target genes to mediate these breast cancer patient and cellular outcomes." (PMID 38377146, 2024). "This contrasts with TRPS1’s binding pattern in breast cancer cells where i) TRPS1 almost exclusively binds at enhancers, and ii) TRPS1 peaks are strongly enriched for GATA motifs but not C2H2 zinc finger motifs." (PMID 38702730, 2024). "While hormone receptors, mammaglobin, GATA3, and, in some cases, SOX10 remain the primary markers for most subtypes of breast carcinoma, TRPS1 has proven particularly useful in cases where these markers are either absent or equivocal." (PMID 39518009, 2024). "When dealing with breast cancer metastases, primary breast carcinoma with unusual morphology, or triple-negative breast cancers, TRPS1 is often used in conjunction with other IHC markers to increase the diagnostic confidence." (PMID 39518009, 2024).
breast carcinoma (continued). "Knockdown of TRPS1 in various breast cancer cell lines has been shown to increase markers of epithelial to mesenchymal transition and genome instability." (PMID 38377146, 2024). "In breast carcinoma, TRPS1 was identified as a highly specific marker, particularly for TNBC based on TCGA database analysis and immunochemistry." (PMID 38609711, 2024). "In this study, we set out to directly assay the primary effects of TRPS1 on chromatin accessibility, ER binding, and transcription in luminal breast cancer cells." (PMID 38377146, 2024). "While TRPS1 is expressed in a wider range of breast cancer subtypes, the use of SOX10 is generally limited to specific TNBC cases, often as part of a broader panel including GATA3 and CK5/6." (PMID 39518009, 2024). "In this study, we used rapidly inducible targeted protein degradation to systematically determine the primary effects of acute TRPS1 depletion on chromatin accessibility, ER binding, and nascent transcription in a luminal breast cancer cell line." (PMID 38377146, 2024). "A panel made out of a novel marker, MGP, used together with GATA3 and TRPS1 can lead to an increased sensitivity in the recognition of all breast carcinomas." (PMID 39518009, 2024). "Studies have demonstrated that TRPS1 is highly specific for breast cancer when compared with other carcinomas that are commonly found in metastatic sites." (PMID 39518009, 2024). "Here, we use an inducible degron tag system to rapidly deplete endogenously-tagged TRPS1 in luminal breast cancer cells within 30 minutes." (PMID 38377146, 2024). "In breast carcinoma, TRPS1 typically demonstrates nuclear staining, making it a valuable marker for identifying the breast tissue origin, especially in triple-negative breast cancer (TNBC) and luminal subtypes." (PMID 39518009, 2024). "Taken together, these data indicate that TRPS1 influences breast cancer incidence and is required for maximal breast cancer cell fitness." (PMID 38377146, 2024). "TRPS1 activity is particularly high in Luminal B and Basal-like breast cancers which are the most aggressive subtypes." (PMID 38702730, 2024). "TRPS1 is highly expressed in primary breast cancer tissues and has been shown to regulate epithelial–mesenchymal transition (EMT), a process integral to cancer metastasis." (PMID 39518009, 2024). "Eighteen (18/19, 94.7%) metastatic breast carcinomas showed diffuse and strong TRPS1 positivity (histoscore 12)." (PMID 39449380, 2024). "Mechanistically, elevated TRPS1 expression promotes hyperactivity of DNA damage repair (DDR) in breast cancer cells." (PMID 39276941, 2024). "It is important to highlight that TRPS1 immunohistochemical marker is commonly expressed in breast carcinoma, MPD and EMPD, as the present case demonstrates, but has been reported to be positive in cutaneous carcinoma in situ as well." (PMID 38658519, 2024). "TRPS1 (trichorhinophalangeal syndrome type 1) is a protein that has become an important marker for diagnosing breast cancer, especially in difficult-to-diagnose cases like triple-negative breast cancer." (PMID 39518009, 2024). "While TRPS1 is a highly sensitive marker for breast cancer, its presence in other tumor types poses challenges for pathologists." (PMID 39518009, 2024). "In recent years, TRPS1 has gained recognition as a reliable IHC marker in breast cancer pathology due to its consistent overexpression in almost all histopathologic and molecular subtypes of primary breast tumors." (PMID 39518009, 2024). "TRPS1 negativity complicates the classification of certain breast cancer subtypes, particularly TNBC and basal-like breast cancers, where the lack of both TRPS1 and other lineage markers makes accurate subtyping challenging." (PMID 39518009, 2024). "For example, GATA3, ESR1, and TRPS1 were identified as the three leading master regulators in breast cancer." (PMID 37600846, 2023).